PTF1A (pancreas associated transcription factor 1a)
Diseases named in the same sentence as PTF1A in open-access papers (continued):
Sharing a sentence is not in itself a finding about the gene and the disease.
tumor (continued). "Importantly, the analysis of the repressive histone modification H2AK119ub revealed that the Ptf1a and Rbpjl promoter displayed a strong enrichment of H2AK119ub in tumor cells, indicating that acinar specific differentiation genes are persistently silenced during tumor formation." (PMID 26716510, 2016). "Transcriptional changes were extensively studied in both conditions and revealed that a loss of acinar specific transcription factors, such as Gata6, Mist1 and Ptf1a, supports ADM formation and, in presence of mutant Kras, tumor development." (PMID 26716510, 2016). "The distribution of the epigenetic modifications perfectly matches the gene expression data showing a reactivation of the progenitor gene Rbpj and a repression of Ptf1a and Rbpjl in 3D-ADM and tumor cells." (PMID 26716510, 2016). "Expression of K-RasG12D from the endogenous Kras locus in Ptf1a+/Cre;Kras+/LSL-G12D mice is well known to trigger tumor formation in the pancreas." (PMID 26988419, 2016). "The cell lines we used in this study are primary tumor cells derived from a mouse model which spontaneously develops metastatic PDAC and reports pancreatic and pancreas-derived cells by Ptf1a-mediated RFP expression and reports Slug activity via YFP expression." (PMID 31281387, 2019). "Treatment with gemcitabine alone resulted in a 38% decrease in tumor burden in cells not expressing PTF1a." (PMID 29719936, 2018). "In this study, we tested whether induced MIST1 or PTF1a expression in PDAC cells could (i) re‐establish the transcriptional program of differentiated acinar cells and (ii) simultaneously reduce tumor cell properties." (PMID 29719936, 2018). "Unlike other tumor suppressors, however, PTF1A levels are reduced in cancer cells by a mechanism that does not involve a genetic mutation." (PMID 26151762, 2015). "Also, colonies expressed pancreatic acinar (PTF1a, amylase, trypsin) and ductal markers (KRT7) and reliably formed subcutaneous xenografts that faithfully recapitulated the original human tumor histology." (PMID 28526679, 2017). "In the absence of PTF1A, a persistent inflamed microenvironment may have tumor promoter-like activity, enhancing KRAS-MEK-ERK signaling to induce transformation." (PMID 26151762, 2015). "Littermate control mice lacking an inducible Cre recombinase (genotype Ptf1a+/+; KrasLSL-G12D/+; Trp53LSL-R270H/+; Rosa26LSL-mCL/LSL-mCL; or KP) were injected with tamoxifen and monitored for tumor development for up to one year." (PMID 31490946, 2019).
cancer (16 papers, 2014 to 2026). A tumor composed of atypical neoplastic, often pleomorphic cells that invade other tissues. "Here, we demonstrate that loss of Ptf1a leads to upregulation of genes associated with KRAS-dependency in human cancer cells." (PMID 26151762, 2015). "Additionally, induction of PTF1a in PDAC influenced cancer‐associated properties, leading to decreases in cell proliferation, CSC numbers, and repression of ABC efflux transporters resulting in heightened sensitivity to gemcitabine." (PMID 29719936, 2018). "We therefore hypothesized that decreased Ptf1a dosage would promote cancer susceptibility by increasing the rate of PanIN initiation." (PMID 26151762, 2015). "Importantly, induction of PTF1a in PDAC also influenced cancer‐associated properties, leading to a decrease in cell proliferation, cancer stem cell numbers, and repression of key ATP‐binding cassette efflux transporters resulting in heightened sensitivity to gemcitabine." (PMID 29719936, 2018). "The mouse PanIN-PDAC model provides a new experimental system to relate genetic changes in cancer, such as KRAS mutation, to epigenetic changes such as PTF1A downregulation." (PMID 26151762, 2015). "Although there is little evidence demonstrating the involvement of mutated KRAS in MDB development, we were able to reproduce a cancer model with features of pediatric MDB due to the specific expression of KRASG12D in ptf1a-expressing tissues." (PMID 24878567, 2014). "In order to obtain a significant number of cancer lesions, we collected 120 Tg(ptf1a:Gal4)/UAS:eGFP-KRASG12D injected animals." (PMID 24878567, 2014). "However, in all cases PTF1a was more potent in decreasing cancer‐associated gene expression when compared to MIST1‐induced profiles, suggesting that PTF1a has a greater global impact in driving cells toward a quiescent, acinar‐specific phenotype." (PMID 29719936, 2018). "Therefore, a future challenge is to determine how the amount of PTF1A protein is reduced, and in the longer term, to explore if it is possible to reverse cancer progression by forcing cancer cells back into their original differentiation state." (PMID 26151762, 2015). "In this study, we used mouse cancer cell lines generated from mouse models of PanIN (Ptf1a-Cre; KrasG12D; p53f/+) and IPMN (Ptf1a-Cre; KrasG12D; Brg1f/f)." (PMID 32266133, 2020). "We blocked the secretion of exosomes by conditionally knocking out (KO) Rab27a in the healthy pancreas (Pdx1-Flp; Rab27aFrt/Frt) and in PDAC cancer cells using the fast progression PDAC model (PKT iRab27a, Ptf1a-Cre; LSL-KrasG12D/+; Tgfbr2loxP/loxP; R26LSL-FLPoERT2/+; Rab27aFrt/Frt)." (PMID 38383468, 2024). "Thus, progenitor cell and acinar genes within PDAC cells remained accessible to activation by PTF1a and MIST1, revealing that PDAC cells are not irreversibly locked into an undifferentiated cancer cell state." (PMID 29719936, 2018).
pancreas (2 papers, 2020 to 2022). "show that pancreas agenesis mutations disrupt a lead enhancer that activates other PTF1A enhancers in early progenitors of the embryonic pancreas." (PMID 35998583, 2022).
neurodegenerative disease (1 paper, 2018). A disorder of the central nervous system characterized by gradual and progressive loss of neural tissue and neurologic function. "Our work has demonstrated the feasibility of using Ptf1a-reprogrammed iNSCs as a cell replacement therapy to treat neurodegenerative diseases." (PMID 30030434, 2018). "Given the vitality and tripotent differentiation potential of Ptf1a-induced miNSCs in vivo, we tested whether transplanted miNSCs had any therapeutic effect in treating murine neurodegenerative disease models." (PMID 30030434, 2018).
PTF1A also shares sentences with these, for which no sentence is quoted: neonatal diabetes mellitus (3 papers); anemia (2); breast carcinoma (2); congenital hypothyroidism (2); epilepsy (2); hypothyroidism (2); lung carcinoma (2); Wolcott-Rallison syndrome (2); Acidosis (1); adenocarcinoma (1); Alzheimer disease (1); anorectal malformation (1); Ataxia (1); B-Cell lymphomas (1); bladder cancer (1); Cerebellar hypoplasia (1); cholestasis (1); colon cancer (1); deafness (1); DEND syndrome (1); diabetic retinopathy (1); Dias-Logan syndrome (1); enterovirus infection (1); Epiphyseal dysplasia (1); gastrointestinal disease (1); generalized dystonia (1); genetic disease (1); glaucoma (1); hyperferritinemia (1); Hyperglycemia (1).
A further 18 diseases each share a sentence with PTF1A in 1 paper.